HRH1 (histamine receptor H1)
Diseases named in the same sentence as HRH1 in open-access papers (continued):
Sharing a sentence is not in itself a finding about the gene and the disease.
schizophrenia (8 papers, 2016 to 2023). A major psychotic disorder characterized by abnormalities in the perception or expression of reality. "Cinnarizine targets HRH1, which has been linked to schizophrenia etiology." (PMID 31481665, 2019). "Patients with schizophrenia display reduced expression of HRH1 in cholinergic neurons as well as reduced expression of choline acetyltransferase (ChAT)." (PMID 37474883, 2023). "Previous studies have shown abnormal receptor radioligand binding and expression of HRH1 in different brain disorders, such as schizophrenia, depression, and autism." (PMID 37474883, 2023). "Since the post-mortem and neuroimaging studies reveal that cholinergic dysfunction is observed in individuals with schizophrenia, we investigated the level of Hrh1 mRNA in cholinergic neurons by RNAscope in situ hybridization (ISH) in brain samples from adult patients with schizophrenia." (PMID 33602941, 2021). "HRH1, targeted by cinnarizine, was predicted to interact with the schizophrenia gene NAB2." (PMID 31481665, 2019). "The fact that refractory schizophrenia may be treated with clozapine, an HRH1 antagonist, indicates that extra-dopaminergic systems, namely, the histamine neuron system, contribute to schizophrenia etiology." (PMID 31481665, 2019). "Recently, it has been shown that patients with schizophrenia having negative symptoms present decreased HRH1 expression in BF cholinergic neurons and that deletion of Hrh1 in mice cholinergic neurons reduces their interest in social novelty." (PMID 37474883, 2023). "In the present study, we revealed that the Hrh1 mRNA expression in cholinergic neurons was only reduced in patients with schizophrenia having both positive and negative symptoms, but not the patients with schizophrenia having positive symptoms only." (PMID 33602941, 2021). "We found that the male patients with schizophrenia having positive and negative symptoms showed decrease in the Hrh1 mRNA expression (unpaired two-tailed t test, t = 2.593, P = 0.027)." (PMID 33602941, 2021). "Meanwhile, the female patients with schizophrenia having positive and negative symptoms (P < 0.001), but not patients with schizophrenia having positive symptoms only (P = 0.560), showed decrease in the Hrh1 mRNA expression (one-way ANOVA with post hoc Tukey’s test, F2, 11 = 20.070, P = 0.302)." (PMID 33602941, 2021).
COVID-19 (6 papers, 2021 to 2025). A disease caused by infection with severe acute respiratory syndrome coronavirus 2. "Consequently, the manipulation of antihistamines in COVID-19 patients not only abolishes HRH1-mediated viral entry but also cripples ACE2-dependent viral infection." (PMID 39037273, 2024).
diabetes (5 papers, 2017 to 2025). "Overall, these findings suggest that altered miRNA expression following HRH1 activation may play a role in diabetes." (PMID 40667070, 2025).
Anxiety (4 papers, 2019 to 2025). Intense feelings of nervousness, tension, or panic often arise in response to interpersonal stresses. "In agreement with our findings, an Hrh1 knockout study and a pharmacological study using the H1 receptor antagonist diphenhydramine reported that H1 receptor signalling mediated anxiety-like behaviour." (PMID 31712580, 2019).
hepatocellular carcinoma (4 papers, 2016 to 2025). A malignant tumor that arises from hepatocytes. "HRH1 overexpression in hepatocellular carcinoma (HCC) was shown to promote tumor metastasis by inducing matrix metalloproteinase (MMP)-2, and treatment with HRH1 antagonists was reported to decrease the HCC risk in patients with hepatitis B virus (HBV), HCV, or dual infection." (PMID 40113769, 2025).
atherosclerosis (3 papers, 2014 to 2022). A disease characterized by the build-up of fatty material and calcium deposition in the arterial wall resulting in partial or complete occlusion of the arterial lumen. "Mepyramine, one of the HRH1-specific antihistamines highly associated with atherosclerosis, has already been shown to decrease the formation of atherogenic plaques in a mouse model of the disease." (PMID 36313344, 2022). "Cetirizine and fexofenadine are also HRH1-specific antihistamines highly associated with atherosclerosis but neither prevented or reduced atherosclerosis progression in a mouse model of atherosclerosis, and both increased atherosclerotic lesions at low doses." (PMID 36313344, 2022).
autism spectrum disorder (3 papers, 2020 to 2021). A spectrum of developmental disorders that includes autism, and Asperger syndrome. "Histamine dysregulation may have a role in mediating autism spectrum disorder phenotype with altered expression of key histamine signaling genes HNMT, HRH1, HRH2, and HRH3 in post-mortem brains of patients with ASD." (PMID 34335160, 2021).
colon cancer (3 papers, 2022 to 2023). "Another study stated that HRH4 expression in CRC tissue and normal colon mucosa was present, and HRH1, HRH2, and HRH4 in human colon cancer cells: HT29, Caco-2, and HCT116." (PMID 36902343, 2023).
glioma (3 papers, 2017 to 2025). A benign or malignant brain and spinal cord tumor that arises from glial cells (astrocytes, oligodendrocytes, ependymal cells). "We found that HRH1 and CHRM3 were expressed at higher levels in GBM (grade IV) in comparison to lower-grade gliomas (grade II and III), while CHRM1 displayed the opposite trend." (PMID 37760589, 2023). "The well-established antagonist activity of clemastine against H1R and the inhibitory effects of M1R and M3R signaling on oligodendrocyte differentiation prompted us to determine the expression profiles of these three receptor genes (HRH1, CHRM1, and CHRM3) in gliomas." (PMID 37760589, 2023).
ischemia (3 papers, 2016 to 2025). A hypoperfusion of the BLOOD through an organ or tissue caused by a PATHOLOGIC CONSTRICTION or obstruction of its BLOOD VESSELS, or an absence of BLOOD CIRCULATION. "Namely, the peptide reduced the expression of many genes (e.g., P2rx6, Gabra3, Grik4, Oprl1, Glra2, Crhr1, Hrh1, Chrm5, Grik1) related to the neurosignaling system and whose expression was not significantly changed by ischemia itself." (PMID 40650034, 2025).
liver cancer (3 papers, 2022 to 2025). An epithelial or non-epithelial malignant neoplasm that arises from the liver. "Previous in vitro and in vivo investigations showed that agonists of HRH1 such as histamine significantly induced progression (growth and metastasis) of liver cancer via HRH1 which was highly expressed in liver cancer tissues." (PMID 35587368, 2022). "Recently, high expression levels of histamine or HRH1 were observed in different human cancers and were correlated with poor prognoses including in breast, colon, and liver cancers." (PMID 35587368, 2022).
pancreatic cancer (3 papers, 2024 to 2025). "HRH1 blockade was shown to upregulate major histocompatibility complex (MHC)-I expression in pancreatic cancer and enhance CD8+ T cell infiltration." (PMID 40113769, 2025). "Among the pancreatic cancer cell lines studied, KP-2 exhibited the highest level of HRH1 expression." (PMID 38715057, 2024). "We assessed HRH1 expression in pancreatic cancer cell (PCC) specimens from PDAC patients through public data analysis and immunohistochemical (IHC) staining." (PMID 38715057, 2024). "HLA-ABC expression in pancreatic cancer cell lines was increased by HRH1 antagonists." (PMID 38715057, 2024). "The most upregulated miRNA from HRH1 stimulation, miR-502–3p, was associated with multiple enriched pathways related to insulin resistance, including EGFR tyrosine kinase inhibitor resistance, AGE-RAGE signaling pathway in diabetic complications, and pancreatic cancer." (PMID 40667070, 2025). "Here, we hypothesized that HRH1 is related to tumor immunity in PDAC, and combining its antagonist with ICB may enhance the effectiveness of pancreatic cancer treatment." (PMID 38715057, 2024).
Breast Tumors (2 papers, 2016 to 2025). "The neurogenes HRH1 and NRP2 were upregulated in basal-related breast tumors and CD44+ cancer cells and another, STX1A, was upregulated in luminal B and HER2-enriched tumors." (PMID 26673618, 2016).
gastric cancer (2 papers, 2016 to 2023). A primary or metastatic malignant neoplasm involving the stomach. "In gastric cancer, HRH1 is expressed in circulating tumor cells and can be used as a biomarker to predict which patients have minimal residual disease and therefore a higher risk of developing metastases." (PMID 26673618, 2016).
oral squamous cell carcinoma (2 papers, 2022 to 2025). "Histamine receptor H1 (HRH1) was reported to be overexpressed in several cancer types, but its specific functional implications in oral squamous cell carcinoma (OSCC) predominantly remain unexplored." (PMID 40113769, 2025).
rhinitis (2 papers, 2021 to 2025). An inflammation of the mucous membrane lining the nose, usually associated with nasal discharge. "Furthermore, it was found that propolis effectively reduced the expression of Histamine Receptor H1 (H1R) and IL-9 genes and downregulated the protein kinase Cδ (PKCδ) and nuclear factor of activated T-cells (NFAT) signaling pathways in a rhinitis animal model." (PMID 40078415, 2025).
viral infection (2 papers, 2024). "Our resultsshowed that the overexpression of HRH1 significantly augmented viral infection,as indicated by increased numbers of luminescent units along with increased HRH1expression." (PMID 38953634, 2024). "To determine the specific stage of viral infection targeted by HRH1 antagonists,we conducted drug or virus pretreatment assays." (PMID 38953634, 2024). "Antihistamine drugseffectively prevent viral infection by competitively binding to HRH1,thereby disrupting the interaction between the spike protein and itsreceptor." (PMID 38953634, 2024). "HRH1 binds to ACE2 to bindto the viral spike protein and synergistically promotes ACE2-mediated viral entry.Manipulating antihistamine drugs that competitively bind to HRH1 could also abortthe ACE2-mediated enhancement of viral infection." (PMID 38953634, 2024). "To exclude the possibility that endogenous hACE2 proteins within HEK293Tcells might facilitate HRH1-mediated viral infection, we overexpressed HRH1 inhACE2-knockout HEK293T-hACE2-KO cells." (PMID 38953634, 2024). "Interestingly, HRH1 also directly interacted with the hACE2 receptor and synergistically enhanced hACE2-dependent viral infection." (PMID 39037273, 2024). "Having confirmed the ability of HRH1 antagonists to prevent authentic SARS-CoV-2infection and the coalescence of mHRH1 with hACE2 to facilitate viral infection,we hypothesized that these antihistamine drugs might protect against authenticSARS-CoV-2 infection in mouse models." (PMID 38953634, 2024).
abscess (1 paper, 2018). An inflammatory process characterized by the accumulation of pus within a newly formed tissue cavity which is the result of a bacterial, fungal, or parasitic infection or the presence of a foreign body. "GO analysis with the unique differential promoters involved in Munro’s abscess formation revealed neutrophil and leukocyte chemotaxis as the highest enriched biological processes which include genes like HRH1, PDE4D, CCL25, AIF1, ADAM10, FFAR2, IL1B and TREM1." (PMID 30092825, 2018).
acne (1 paper, 2024). An inflammatory process of the sebaceous glands which is characterized by comedones, nodules, papules and/or pustules on the skin. "Our analysis also spotlighted several other genes implicated in acne risk, including HRH1, ATG7, and VGLL4." (PMID 39297226, 2024). "Our research, through colocalization analysis, has identified genes such as HRH1, ATG7, and VGLL4 as related to the risk of acne, but currently, the clinical applications of these genes or proteins are mainly still in the research phase." (PMID 39297226, 2024).
alcoholic fatty liver disease (1 paper, 2022). Lipid infiltration of the hepatic parenchymal cells that is due to alcohol abuse. "SAveRUNNER predicted that cyproheptadine, which targets both HRH1 and the serotonin 2A receptor, HTR2A, instead of HRH1 alone would be the best antihistamine for treating non-alcoholic fatty liver disease." (PMID 36313344, 2022).
attention deficit-hyperactivity disorder (1 paper, 2023). A disorder characterized by a marked pattern of inattention and/or hyperactivity-impulsivity that is inconsistent with developmental level and clearly interferes with functioning in at least two settings (e.g. at home and at school). "In attention-deficit hyperactivity disorder and Gilles de la Tourette syndrome, we decided to investigate the consequences of hrh1-loss of function on relevant behaviors." (PMID 37474883, 2023).
bladder overactivity (1 paper, 2024). "In summary, our data suggest that VCR exposure enhances histamine sensitivity in the bladder, and Hrh1 may serve as a promising therapeutic target for managing VCR-induced bladder overactivity." (PMID 38951167, 2024).
cervical tumors (1 paper, 2020). "In addition, the expression of two kinds of main histamine receptor (HRH1 and HRH3) in cervical tumors was measured to ascertain that apigenin did not alter the ER signal by protecting HeLa cells from receiving histamine signal." (PMID 32340124, 2020).
chronic myelomonocytic leukaemia (1 paper, 2020). "To inquire on that open question, we first examined HRH1 expression in blood cell subsets from healthy donors, as well as in samples from patients with AML and the related myeloid malignancies chronic myelomonocytic leukaemia (CMML) and myelodysplastic syndromes (MDS)." (PMID 33080103, 2020).
endometrial cancer (1 paper, 2021). Primary or metastatic malignant neoplasm involving the endometrium (mucous membrane that lines the endometrial cavity). "The analysis showed that the expression of HRH1, HRH2, and HRH3 increased with the progression of endometrial cancer." (PMID 34768392, 2021).
endometriosis (1 paper, 2025). The growth of functional endometrial tissue in anatomic sites outside the uterine body. "All four receptors (HRH1-4) were detected with the strongest signals in peritoneal and ovarian endometriosis, in epithelial cells, endometriosis-associated immune cells, and nerve fibers associated with endometriosis." (PMID 41516088, 2025). "In deep infiltrating endometriosis, 20% of HRH1-positive nerves colocalized with substance P, and 40% showed colocalization with both tyrosine hydroxylase and VIP." (PMID 41516088, 2025). "In deep infiltrating endometriosis tissues, HRH1-, HRH2-, and HRH3-positive nerve fibers were identified in 15.63%, 52.17%, and 28.95% of nerves, respectively, whereas ovarian endometriosis showed no receptor-positive nerve fibers." (PMID 41516088, 2025). "Using gene expression data from the database provided by the University of Turku, we analyzed the expression levels of histamine receptors HRH1, HRH2, HRH3, and HRH4 across various endometriosis subtypes and control tissues." (PMID 41516088, 2025). "This pattern suggests that histamine signaling via HRH1 and HRH2 may influence both nociceptive and autonomic components within deep infiltrating endometriosis lesions." (PMID 41516088, 2025).
glaucoma (1 paper, 2022). Increased pressure in the eyeball due to obstruction of the outflow of aqueous humor. "This readily testable small molecule drug is a promising neuroprotectant, and HRH1 is a potential therapeutic target for glaucoma and other neurodegenerative diseases associated with ER stress." (PMID 36357388, 2022). "In the SOHU glaucoma model, HRH1 KD also showed a significantly thicker GCC and greater survival of RGC somata and axons than controls." (PMID 36357388, 2022). "This study found that FDA approved drug, maprotiline, inhibits histamine receptor H1-mediated ER stress and provides significant neuroprotection in mouse glaucoma model." (PMID 36357388, 2022). "In this work we establish maprotiline as a candidate neuroprotectant and HRH1 as a potential therapeutic target for glaucoma." (PMID 36357388, 2022). "We found that both systemic administration of maprotiline and locally applied CRISPR-mediated RGC-specific HRH1 inhibition achieve significant neuroprotection and visual function recovery in in vivo mouse models of glaucoma and traumatic ON injury." (PMID 36357388, 2022). "Our in vivo findings establish maprotiline as a candidate neuroprotectant and HRH1 as a potential therapeutic target for glaucoma, and possibly for neurodegenerative diseases more generally." (PMID 36357388, 2022). "We injected the mixture of AAV-mSncg-Cas9 + AAV-mouse HRH1-gRNAs or AAV-control gRNAs intravitreally into one of a mouse’s eyes five weeks before ONC (for traumatic ON injury model) or SO intracameral injection (SOHU glaucoma model) and used the contralateral eye as sham control." (PMID 36357388, 2022). "Immunostaining showed HRH1 protein levels to be more extensive in RGCs, and crush injury, but not glaucoma, decreased protein expression in RGCs." (PMID 36357388, 2022).
head and neck squamous cell carcinoma (1 paper, 2022). A squamous cell carcinoma that arises from any of the following anatomic sites: lip and oral cavity, nasal cavity, paranasal sinuses, pharynx, larynx, and salivary glands. "Furthermore, analyses of TCGA and GEO databases revealed that HRH1 expression levels were upregulated in head and neck squamous cell carcinoma (HNSCC) and OSCC tissues compared to normal tissues and were correlated with larger tumor sizes and poorer prognoses." (PMID 35587368, 2022).
migraine (1 paper, 2018). "However, histamine release alone is not responsible for spontaneous migraine attacks, as histamine-receptor H1 and H2 blockade is a poor prophylaxis for migraine sufferers, indicating a discrepancy between genuine migraine attacks as compared to histamine-provoked attacks." (PMID 29460121, 2018).
myeloid malignancies (1 paper, 2020). "Rather than playing a lead role in myeloid malignancies, HRH1 may thus reflect the maturation state of abnormally differentiated cells." (PMID 33080103, 2020).
neuroblastoma (1 paper, 2025). Neuroblastoma (NB) is the most common solid, extracranial childhood tumor. "Second, the experimental validation of HRH1’s role in ER exodosis was primarily conducted in SH-SY5Y human neuroblastoma cells." (PMID 40791405, 2025).
Optic neuropathy (1 paper, 2022). "They share similar tricyclic chemical structures and a common antagonistic target, histamine receptor H1 (HRH1), through which we find that they restore ER homeostasis and achieve significant neuroprotection of RGCs and ONs in vivo in two mouse optic neuropathy models." (PMID 36357388, 2022). "We next investigated whether HRH1 inhibition also furnishes neuroprotection in two mouse optic neuropathy models." (PMID 36357388, 2022). "Therefore, like maprotiline treatment, blocking HRH1 significantly protects RGCs and ONs and preserves visual functions in two mouse optic neuropathy models, indicating the promising therapeutic potential of HRH1 inhibition in traumatic and glaucomatous neurodegeneration." (PMID 36357388, 2022).
oral cancer (1 paper, 2022). "Adjusted odds ratios (AORs) and 95% confidence intervals (CIs) of oral cancer associated with histamine receptor H1 (HRH1) genotypic frequencies." (PMID 35587368, 2022). "We further analyzed correlations of HRH1 expression levels and their clinical significance or survival rates in oral cancer, by examining cases of HNSCCs from The Cancer Genome Atlas (TCGA) dataset." (PMID 35587368, 2022). "Adjusted odds ratios (AORs) and 95% confidence intervals (CIs) of clinical statuses associated with genotypic frequencies of histamine receptor H1 (HRH1) rs901865 and rs346074 in male oral cancer patients." (PMID 35587368, 2022). "Taken together, downregulated levels of HRH4 together with upregulated levels of HRH1 and HRH2 may play critical roles in tumorigenesis of oral cancer." (PMID 35587368, 2022).